APC (APC regulator of Wnt signaling pathway)
Diseases named in the same sentence as APC in open-access papers (continued):
Sharing a sentence is not in itself a finding about the gene and the disease.
tumor (continued). "For instance, oncomiRNAs like miR-21 and miR-155 enhance tumor cell proliferation and invasion by targeting tumor-suppressor genes, including APC, thereby promoting CRC aggressiveness." (PMID 40943532, 2025). "Wild-type APC acts as a scaffold protein for the β-catenin destruction complex, functioning as a tumor suppressor via regulation of the WNT pathway." (PMID 41091816, 2025). "DSS-treated KRAS mut mice remained tumor-free, but APC and APC; KRAS mut mice developed multiple tumors throughout the colon." (PMID 41285904, 2025). "Case 6, which had the highest number of SNVs, had missense mutations in ATM, POLE and BRCA2, as well as known pathogenic mutations from ClinVar in MSH6, RAD50, APC and NF1, likely explaining the high mutational load in this tumor." (PMID 40670673, 2025). "In the Wnt/β-catenin signaling pathway, which regulates at least 80 target genes, normal expression of the APC gene ensures proper degradation of β-catenin through phosphorylation and ubiquitination, thereby suppressing tumor formation." (PMID 40429703, 2025). "On the other hand, we report the somatic mutational landscape of HCC in our cohort, identified exclusively in the tumor tissues, with APC (100%), ALK (94%), HNF1A (56%), CDKN2A and HRAS (50%) emerging as the most frequently mutated genes." (PMID 41567639, 2025). "Increased p-YAP is linked to APC mutations and abnormal WNT/β-catenin pathway, synergistically interacting with nuclear β-catenin for advanced tumor characteristics." (PMID 39977302, 2025). "Among the four subclusters, the tumor epithelial cells from the APC wild-type samples were mainly in the 0 cluster, which presented high SCC signature scores." (PMID 40357363, 2025). "The APC gene is a well-established tumor suppressor in CRC, playing a central role in regulating the Wnt signaling pathway and maintaining cellular homeostasis." (PMID 40722723, 2025). "We aimed to investigate the progression of APC Min/+ from tumorigenesis to the stabilization of tumor numbers, spanning from 18 days to 90 days, to describe the changes in tumor tissue." (PMID 41009818, 2025). "APC, as a classic tumour suppressor, requires two hits to inactivate its tumour suppressor activity, and based on the location of the somatic c.3924_3925insA, loss of the heterozygosity (LOH) of the wildtype allele is expected." (PMID 40866199, 2025). "APC mutation can stabilize both β-catenin and RAS (especially mutant KRAS) proteins, leading to tumor initiation and progression." (PMID 41294868, 2025).
tumor (continued). "Direct transformation of cancer cells into tumor‐reprogrammed APC (TR‐APC) using bone marrow lineage reprogramming activates endogenous tumor‐associated antigens (TAAs)‐specific T cells for leukemia therapy." (PMID 40395752, 2025). "After a revision of literature, we think that a possible common mechanism for the occurrence of these two kinds of neoplasms can be identified in an alteration of the WNT/APC/β‐catenin pathway." (PMID 40348604, 2025). "Proto-oncogene c-Myc is an essential determinant of cell proliferation and a critical mediator of the early stages of neoplasia in CRC, following loss of APC." (PMID 39996767, 2025). "The loss of PMS2 appears to occur rather as a secondary event following a neoplasia-inducing variant in pMMR CRC, such as pathogenic APC variants." (PMID 40612339, 2025). "Given the young age at developing duodenal adenomas, germline diagnostic sequencing of the most common polyposis-associated genes (APC, MUTYH, NTHL1, POLE, POLD1, AXIN2, and MLH3) was performed on leukocyte DNA, a “tumor-naïve” approach." (PMID 40956995, 2025). "The KEGG biological term enrichment analysis of the mRNAs of this subnetwork revealed biological pathways associated with cell proliferation and differenciation involving the tumor suppressor genes APC and SMAD2." (PMID 38302900, 2024). "APC, a key gene involved in tumor suppression, is essential in regulating intestinal mucosal epithelial cells by regulating cell proliferation, differentiation, apoptosis, and cell cycle." (PMID 39439901, 2024). "The initiation and progression of CRC are mediated by the truncated APC, leading to a gain of function, instead of its tumor-suppressive action, leading to activation of the Wnt-signaling pathway and aberrant modulation of other factors." (PMID 39056802, 2024). "Preclinical studies using tankyrase inhibitors, such as G007-LK, have demonstrated the potential to restore β-catenin degradation and inhibit tumor growth in APC-mutant CRC models." (PMID 39684219, 2024). "The adenomatous polyposis coli (APC) is a prominent tumor suppression gene; however, the APC gene is frequently mutated and promotes CRC onset and development." (PMID 39057088, 2024). "Research has found that TTK can accelerate the progression of tumors by promoting APC/C-CDC20-mediated mitosis in tumor cells." (PMID 39100078, 2024). "Treatment with the JNK inhibitor SP600125, alone or combined with H2O2, decreased APC expression to less than 5% of tumor cells." (PMID 39200280, 2024). "Other genes such as APC, KRAS, VHL and IDH1 were highly enriched for mutations in only one or two tumor types." (PMID 38200255, 2024). "In the SW480 cell line, H2O2 [0.05 mM] increased cytoplasmic APC expression from 5% to 80% of tumor cells." (PMID 39200280, 2024). "Accordingly, we seeded LS174T APC-WT or APC-m4 cells in 96-well ultra-low attachment culture plates to generate tumor spheroids." (PMID 38680662, 2024). "Secondly, compensatory function by axin (another component of the β-catenin/GSK-3β/APC/axin complex) with tumor suppressor activity has already been confirmed." (PMID 38903727, 2024). "This suggests that PLK1 helps to maintain the mitotic checkpoint in these cells, and its inhibition can accelerate the development of adenomatous polyps, supporting a “tumor-suppressor function” for PLK1 in APC-ΔC-expressing colon cells." (PMID 39273409, 2024).
tumor (continued). "Overall, the interaction between PLK1 and APC in cancer cells is complex and can have both tumor-promoting and tumor-suppressing effects, depending on the context." (PMID 39273409, 2024). "APC is a tumor suppressor gene that exerts its effect through the regulation of the Wnt signaling pathway." (PMID 39125758, 2024). "Other gut pathogens secrete volatile organic compounds that generate oxidative stress, activating Wnt/β-catenin signaling through phosphorylation and degradation of the APC tumor suppressor." (PMID 39273409, 2024). "The APC gene functions as a tumor suppressor, regulating the WNT signaling pathway and maintaining genomic stability." (PMID 39021676, 2024). "In our study, this type of tumor stained differently than adenocarcinomas for CK18 and exhibited mutations for Notch 1 and APC." (PMID 39123450, 2024). "Though the individual mutation of APC and KRAS influences tumor growth and survival, the severity of CRC significantly rises when there are both mutations in the cell." (PMID 39056802, 2024). "APC is a tumor suppressor gene responsible for the production of adenomatous polyposis coli (APC), which regulates β-catenin and plays a crucial role in cell communication, signaling, and growth." (PMID 39632802, 2024). "CDKN2A is a known tumour suppressor gene involved in cell cycle regulation, while APC is a critical component of the Wnt signalling pathway." (PMID 38279519, 2024). "Enforcing miR-19a expression can override APC’s tumor-suppressive effects, while knocking down miR-19a in cancer cells with compromised APC function reduces their aggressiveness in vitro." (PMID 38534736, 2024). "Simultaneous activation of two critical pathways, Wnt signaling through the loss of the Wnt antagonist APC and constitutive PI3K activation, resulted in enhanced tumor initiation and promotion in mice." (PMID 38891932, 2024). "The possible driver genes in the tumor sample were screened as ARID1B, MAX, NOTCH2 and APC, in which a missense mutation of base C instead of base T occurred in the NOTCH2 gene located at position 120,471,691 on chromosome 1." (PMID 38730456, 2024). "The cessation of proliferation associated with the high MAPK activity and EMT has been reported specifically at the leading tumor edge in the APC-mutant CRC tumors." (PMID 39594797, 2024). "The inter-group expression difference analyses for tumor genes implied that APC, ATM, BARD1, BRAF, and BRCA1 gene expression varied among patients in these two groups." (PMID 38338834, 2024). "Together, these findings uncover important roles for APC at early stages of tumor cell protrusions and invasiveness." (PMID 38680662, 2024). "These in vitro studies indicate that in HCC anti-tumour T cells can be induced when tumour antigens are effectively presented by well matured APC." (PMID 38440738, 2024).
tumor (continued). "The leucine-rich repeat-containing G-protein coupled receptor 5 (Lrg5) marks intestinal stem cells, driving tumor growth when adenomatous polyposis coli (APC) is lost." (PMID 39335624, 2024). "Further results indicate that the heterogeneity of primary tumor plays a critical role in its metastatic ability, a notion corroborated by findings in the APC gene model." (PMID 39307879, 2024). "This aberrant activity is driven by various oncogenic pathways and dysfunctions in tumor suppressors, including mutated or amplified EGFR, PI3K, Akt, Ras, and Raf, as well as impaired PTEN, APC, LKB1/STK11, and Gator1." (PMID 38560690, 2024). "Our study revealed significant dynamic changes in BRAF, APC, and GNAS mutations during ICI treatment, shedding light on the tumor’s molecular evolution under therapeutic pressure." (PMID 39796090, 2024). "Among these genes, APC exhibited the highest frequency of methylation in both mucosa and tumor tissue, yet the methylation level in mucosa remained below 10 % and did not correlate with that in tumors." (PMID 39309195, 2024). "Recent evidence has shown that APC can regulate the response of tumor cells to chemotherapy by modulating epithelial and TME signals." (PMID 39200280, 2024). "Another significant tumor suppressor gene, APC, is integral to the Wnt signaling pathway overseeing cell proliferation and differentiation." (PMID 39415846, 2024). "This assay is based on epigenetic changes associated with the risk of PC development existing/occurring adjacent to tumor foci (halo effect) and evaluates quantitatively the DNA methylation level of GSTP1, APC, and RASSF1." (PMID 38254807, 2024). "To enhance our understanding of KLK6’s role in mutant APC-driven CRC tumor development, we analyzed KLK6 expression in the intestinal tract of the ApcMin/+ mouse." (PMID 39594797, 2024). "The process is initiated by the inactivation of the APC gene, which normally functions as a tumor suppressor to regulate cell growth and division." (PMID 39273409, 2024). "Traces of APC tumor suppressor activity are detected in both the nucleus and cytoplasm, indicating its antioncogenic role, particularly with regard to Wnt signaling canonical pathways." (PMID 37901797, 2023). "Taken together, our results showed that deletion of Drp1 in APC-derived tumor organoids promotes the expression of GYS1 and glycogen accumulation." (PMID 37816729, 2023).
tumor (continued). "Further, softening/stiffened tumor cells facilitated/suppressed the formation and growth of tumor spheroids, while concurrently overexpressing/silencing APC diminished this effect and reduced/enhanced these abilities to the control or even lower/higher level." (PMID 37746658, 2023). "In 2019, CRISPR/Cas9 screening was conducted to verify the function of the introduced mutant genes in the AK (APC, KRAS) mutations intestinal tumor organoid model." (PMID 37993945, 2023). "Mutation-induced activation of Wnt-β-catenin signalling is a frequent driving event in tumours, especially in CRC, where APC mutation-induced activation account for approximately 67%." (PMID 37409251, 2023). "DNA sequencing confirmed that these organoids harbored mutations in CRC genes (APC, KRAS, and PIK3CA) that corresponded to the mutations found in the original tumor." (PMID 37085135, 2023). "The APC tumor suppressor is an essential component of a cytoplasmic protein complex that targets β-catenin for destruction." (PMID 37943958, 2023). "These miRNAs either function as a oncomiR and target the main suppressors of Wnt/β-catenin signaling, especially APC, or have a tumor suppressive role by targeting vital mediators of this pathway, such as β-catenin." (PMID 37386429, 2023). "In the patients’ tumor lysates, we found that decreased APC levels trended with an increase in MDR1 protein levels (r = −0.3176), but this was not significant (p = 0.4049)." (PMID 37108784, 2023). "Different APC mutations lead to different levels of WNT/b‐catenin signaling pathway activation and are associated with the characteristics of different tumor sites in CRC." (PMID 37096801, 2023). "Next-generation sequencing revealed an APC mutation and a TERT promoter mutation in both tumor parts with the former being associated with the underlining FAP, the latter being potentially associated with an adverse outcome." (PMID 37249797, 2023). "We note multiple network connections between BUB1 and HDAC1, as well as connections between BUB1 and each of CDK1 (cell-cycle transition regulator) and APC (a tumor-suppressor protein within the Wnt signaling pathway)." (PMID 38030619, 2023). "Inactivation of APC promotes tumor progression by increasing WNT/β-catenin signaling and was observed in 9/11 DLBCL cell lines (except SU-DHL-6 and NU-DUL-1) and 8/1295 patients in cBioPortal." (PMID 36831263, 2023). "The role of APC/C in mitotic progression makes it an important target for inducing mitotic arrest and subsequent tumour death." (PMID 36881608, 2023).